MMP2 (matrix metallopeptidase 2)
Diseases named in the same sentence as MMP2 in open-access papers (continued):
Sharing a sentence is not in itself a finding about the gene and the disease.
tumor (continued). "Among MMPs, MMP-2 (gelatinase-A) and MMP-9 (gelatinase-B) are particularly upregulated in SACC and contribute to the invasion of tumor cells by degrading the ECM." (PMID 22200897, 2012). "MMP2 and MMP9, the key enzymes for degrading type IV collagen, are believed to play a critical role in tumor invasion and metastasis." (PMID 22479608, 2012). "Since MMPs play critical roles in tumor cells invasion, we examined the effect of blocking EMMPRIN by its antibody on the enzyme activity of MMP-2 and MMP-9 using gelatin zymography." (PMID 22200897, 2012). "MMPs, especially MMP-2 and MMP-9 play key roles in tumor cell invasion and metastasis due to their ability to degrade type IV collagen, a major component of the ECM." (PMID 22736175, 2012). "Considering activation of MMPs, MT1-MMP is a key enzyme in tumor angiogenesis and metastasis: it hydrolyzes a variety of ECM components, and is a physiological activator of pro-MMP-2 and MMP-9." (PMID 22695075, 2012). "64Cu-DOTA-CTT was found to inhibit MMP-2 (EC50 = 8.7 μM) and MMP-9 (EC50 = 18.2 μM) with similar affinity as CTT (EC50 = 13.2 and 11.0 μM, respectively), but in vivo was a poor tumor imaging agent due to its low affinity and instability." (PMID 23201642, 2012). "In the tumor microenvironment, migration, invasion, and neovascularization are critically regulated by proangiogenic factors such as VEGF and MMP-2 secreted by tumor cells." (PMID 22016776, 2011). "Members of the MMP family of proteins promote tumor angiogenesis as well as cellular detachment, invasion, and metastasis, and some MMP family members, including MMP-2 and MMP-9, are reported to be regulated by IL-8 expression." (PMID 22235381, 2011). "The activation of MMP-2 and MMP-9 is in a tumor-specific manner and correlates with metastatic abilities and poor prognosis." (PMID 21955589, 2011). "Among the MMPs, gelatinase A (MMP-2) is the most abundant MMP and frequently correlates with malignant progression and invasive behavior of tumor cells." (PMID 21762534, 2011). "Reversion-inducing cysteine-rich protein with Kazal motifs (RECK) protein is known to inhibit MMP-2 and MMP-9 activities and lead to strong suppression of invasion, metastasis, and tumor angiogenesis." (PMID 21573219, 2011). "In particular, MMP-2 and MMP-9, which can degrade ECM and activate many growth factors, play an important role in tumor invasion and metastasis." (PMID 22219636, 2011). "The consensus of the classifiers identifies DCLK3, MMP2, TGM3 as oncogenes and PIK3C3 and EPHA3 as tumor suppressors." (PMID 21575214, 2011). "IL-8 induces MMP-2 and MMP-9 expression in bladder cancer and melanoma cell lines, which contributed to increased tumor cell invasion in vitro." (PMID 22235381, 2011). "Although OSM has various and at times contradictory functions in many tumor types, in our cell lines OSM enhanced MMP2 and VEGF expression and function in part through STAT3 activation, thereby promoting tumor cell invasion." (PMID 21481226, 2011). "Expression of galectin-1 is upregulated in various types of tumors and is reported to mediate tumor invasion and metastasis by increasing expression of matrix metalloproteinase MMP-9 and MMP-2 and promoting reorganization of the actin cytoskeleton." (PMID 21687633, 2011). "Activity of MMP-2 was markedly, activity of MMP-9 was even significantly increased in tumour cells overexpressing FL-L1CAM in vitro." (PMID 21541352, 2011). "We have previously demonstrated that both canine and human OSA cell lines, as well as 8 fresh canine OSA tumor samples, exhibit constitutive phosphorylation of STAT3, and that this correlates with enhanced expression of matrix metalloproteinase-2 (MMP2)." (PMID 21481226, 2011). "STAT3 is known to enhance tumor cell invasion, metastasis, and angiogenesis through enhanced expression of VEGF and MMP2." (PMID 21443800, 2011).
tumor (continued). "The enzymatic activities of MMP-2 and MMP-9 were quantified by gelatin-zymography of the same homogenized tumor tissues and plasma from selected patients." (PMID 21726449, 2011). "We next determined the expression levels of MMP-2 and MMP-9, two key matrix metalloproteases involved in the degradation of the basement membrane, and frequently upregulated in invading tumor cells." (PMID 21595927, 2011). "We recently revealed that p37 promoted tumor cell motility, migration and invasion in vitro and enhanced tumor cell metastasis in C57BL/6 mice, which was mainly mediated by matrix metalloproteinase-2 (MMP-2) and the EGFR/MEK/ERK pathway." (PMID 21062494, 2010). "In the current study, we revealed that the PCs can also control the activity of MMP-2 by acting on the expression levels of MMP-2 inhibitors TIMP-1 and TIMP-2 and the levels of uPAR and PAI-1 in tumor cells." (PMID 20404912, 2010). "We therefore sought to examine the effects of resveratrol on MMP-2 and MMP-9 expressions in tumor tissues derived from xenografted nude mice by immunohistochemistry and Western blot analysis." (PMID 21209944, 2010). "Since MMP-2 and MMP-9 play critical role in tumor cell invasion, we examined the effects of CD147 silencing on the enzyme activities of MMP-2 and MMP-9 using gelatin zymography." (PMID 20525232, 2010). "Compared to the low grading group, the expression levels of MMP-2, MMP-9, as well as the tumor edema index (EI), enhanced percentage (EP) and maximum diameters were significantly greater in the high grading group." (PMID 23554622, 2010). "MMP-2 and −9 have been shown to be important in both normal corneal wound healing and EMT-like changes in tumor formation." (PMID 21179238, 2010). "Accordingly, tumor allografts in knockout mice for growth factors such as FGF-2 and MMPs such as MMP-2 and MMP-9 exhibit significantly reduced tumor growth and tumor-induced angiogenesis." (PMID 20804551, 2010). "Tumor cells respond to IFNγ by suppressing the expression of MMP-9 and MMP-2 genes, which are involved in the invasion and angiogenesis process of malignant tumors." (PMID 20157617, 2010). "The MMPs (particularly MMP-2 and MMP-9) and VEGF expression has been studied also in three nasopharyngeal carcinoma human cell lines as factors that can contribute to tumor development and aggressiveness under stimulation of catecholamines." (PMID 20585601, 2010). "Dz13 upregulated the matrix metalloproteinase (MMP)-2 and MMP-9, and decreased expression of MT1-MMP (MMP-14) in cultured tumour cells." (PMID 20334687, 2010). "In this context matrix metalloproteinases and in particular MMP2 and MMP9 are of crucial significance for tumor development and progression." (PMID 20602761, 2010). "In other systems, expression of α1-PDX in tumor cells blocked the maturation of MT1-MMP, leading to reduced MMP-2 activity and cell invasion." (PMID 20404912, 2010). "When IHC was performed, a consistent decrease in MMP-2 and MMP-9 levels was noted in the Dz13 cohort of animals compared to both the saline-treated and Scr-treated tumours." (PMID 20334687, 2010). "MMP-2 and MMP-9 are among the known factors that promote tumor cell motility, invasiveness, and epithelial-mesenchymal transition." (PMID 21203518, 2010). "A number of factors, which include matrix metalloproteinase 2 (MMP-2) and vascular endothelial growth factor (VEGF), are involved in tumor metastasis." (PMID 20170548, 2010). "CREB regulates the expression of genes that suppress apoptosis, induce cell proliferation and mediate inflammation and tumor metastasis such as BCL-2, HER-2, IL-8 and MMP-2." (PMID 20805990, 2010). "MMP-2 and MT1-MMP+ tumor cells were often restricted to the interface between the tumor invasive part and stroma." (PMID 20631829, 2010). "The gelatinases MMP-2 and MMP-9, which specifically degrade collagen IV, are important for initiation and development of tumor vascularization." (PMID 23658855, 2010).
tumor (continued). "MMP-2, MMP-9, and uPA are known to be involved in the degradation of extracellular matrix and play a critical role in tumor invasion and metastasis." (PMID 20429953, 2010). "Tumors in stressed animals showed markedly increased vascularization and enhanced expression of VEGF, MMP-2, and MMP-9; it seems that angiogenic processes mediate the effects of stress on tumor growth in vivo." (PMID 20585601, 2010). "An important characteristic of IL-8 is its ability to increase levels of MMP-2 which degrades the EC basement membrane and remodels the ECM, initiating the early phase of tumor angiogeneses." (PMID 20445741, 2010). "As type IV collagen is one of the integral components of basement membrane (BM), the uncontrolled expression of two type IV collagenases, MMP-2 and MMP-9, is believed to play a critical role in the invasion of BM by tumor cells." (PMID 19930697, 2009). "In PICP-treated tumors the concurrent low expression of RECK and high expression of MMP-9, and the induction in tumor cells expression of MT1-MMP and MMP-2 will push up the balance of proteolysis compared to control." (PMID 19226458, 2009). "MMP-2 (gelatinase-A) and MMP-9 (gelatinase-B) can both degrade the type IV collagen of basement membranes, the first barrier to tumor invasion." (PMID 19930697, 2009). "The results demonstrate that the relative expression levels of MMP-2 and MMP-14 of tumor samples were significantly higher than those of adjacent non-tumor tissue (p = 0.0202 and p < 0.0001, respectively)." (PMID 19144199, 2009). "Our results revealed that after separation, the metastasis potential of NPC-BM29 was confirmed by increased expression of 92-kDa type IV collagenases/gelatinase B (MMP-2 and MMP-9); both enzymes are involved in tumor cell invasion and metastasis." (PMID 19930697, 2009). "The activity of MMP-2 and MMP-9 in the tumor tissue was also detected by the gelatin zymography assay." (PMID 19228418, 2009). "In the in vitro analysis, IFN-γ can reduce the activity of MMP-2 and MMP-9, which are the key modulators of tumor invasion." (PMID 19228418, 2009). "The results indicated that the ratios between MMP-2/RECK, MMP-9/RECK and MMP-14/RECK were significantly higher in the tumor than in adjacent non-tumor tissue samples (p = 0.0024, p = 0.0001 and p < 0.0001, respectively)." (PMID 19144199, 2009). "The positive cell number of CXCL12, CXCR4, MMP-2, MMP-9 and NGF expression of tumor cells in CXCL12-treated group was the highest." (PMID 18983683, 2008). "We therefore sought to examine the effects of curcumin on MMP-2, MMP-9, and uPA on tumor tissues derived from xenografted nude mice." (PMID 18226269, 2008). "The positive positions of tumor cells for VEGF, NF-κB, MMP-2 and MMP-9 staining were located in the cytoplasm and for PCNA in the nucleus." (PMID 18983651, 2008). "MMP-2 and MMP-9 are members of MMPs family and they can functionally degrade collagen IV in ECM, a step essential for tumor invasion and metastasis." (PMID 18983651, 2008). "MMP-2 is an ECM-degradation proteinase that secreted from invasive cancer cells and plays an important role in tumor metastasis regulation." (PMID 18597698, 2008). "These CD34+ iMCs promote tumour growth by expression of the matrix metalloproteinases, MMP9 and MMP2, and the CC-chemokine receptor 1 (CCR1), and migrate towards the CCR1 ligand CCL9, highly increased in the tumour epithelium." (PMID 18506144, 2008). "We have previously reported that mRNAs for several MMPs, including Mmp2, Mmp3, Mmp11 and Mmp14 are expressed in the MMTV-PyMT tumor stroma." (PMID 18698413, 2008). "Blocking MMPs activity specially MMP-2 and MMP-9 has been implicate to inhibit tumor invasion and angiogenesis." (PMID 19662219, 2007). "In relation to tumour progression, MMP-1 has received relatively little attention compared to the basement membrane-degrading proteinases (MMP-2, -9)." (PMID 17311017, 2007).
tumor (continued). "Collectively, these data suggest a role for fibroblast-derived MMP-2 and MT1-MMP in HNSCC tumor invasion in vitro and tumor growth in vivo." (PMID 16515711, 2006). "In HT1080 tumor cells, both protein and mRNA levels of TIMP1, TIMP2, MMP2 and MMP9 are increased by butyrate treatment." (PMID 16972989, 2006). "Both MMP2 and MMP9, which degrade type IV collagen, have been shown to increase expression in tumour cells and correlated with the malignant phenotype." (PMID 16495926, 2006). "In summary, MMP-2, MT1-MMP and the previously unreported MMP-28 were very highly expressed in tumour samples." (PMID 16465195, 2006). "Our data suggest a role for MMP-2 during in vitro invasion and MMP-9 and MMP-2 during in vivo tumor cell growth." (PMID 16515711, 2006). "The Hepatocyte Growth Factor (HGF) receptor c-MET tyrosine kinase is expressed on epithelially derived tumour cells, and is involved in HGF mediated activation of both MMP2 and MT1-MMP." (PMID 16465195, 2006). "Using an in vitro collagen invasion model and an orthotopic model of tumor growth, we identified a role for MMP-2 and MT1-MMP in tumor growth and invasion." (PMID 16515711, 2006). "In the in vivo setting, both MMP-2 and MMP-9 null fibroblasts decreased FaDu tumor volume compared to wild-type fibroblasts, but MMP-2 and MMP-9 null fibroblasts promoted 100% tumor formation." (PMID 16515711, 2006). "Co-injection of FaDu tumor cells with fibroblasts in an orthotopic oral cavity SCID mouse model demonstrated a reduction of tumor volume using MMP-9 and MMP-2 null fibroblasts (48% and 49%, respectively) compared to WT fibroblasts." (PMID 16515711, 2006). "Although MMP-2 null and MMP-9 null fibroblasts formed smaller tumors in vivo, the take rate for these fibroblasts in combination with tumor cells was 100% of injected animals." (PMID 16515711, 2006). "In summary, MMP-2, MT1-MMP and the previously unreported MMP-28 were very highly expressed in tumour samples while MMPs 1, 7, 9, 11, 15, 19 and 23 were highly expressed." (PMID 16465195, 2006). "MMP2 and TIMP2 were the major secretory proteins found in A549 tumour-conditioned medium, whereas MMP9 and TIMP1 were the key proteinases secreted by MDA-MB-231 cells." (PMID 16495926, 2006). "Tissue inhibitor of metalloprotease 2 (TIMP-2), an endogenous inhibitor of MMP-2, has been shown to inhibit invasion and metastasis and overexpression of TIMP-2 inhibited growth and reduced invasive potential in tumor cells." (PMID 15918904, 2005). "Recently, Schwartz and co-workers found that neutrophil-secreted factors can activate pro-MMP-2, which is important in ECM degradation and tumor cell invasion." (PMID 15555067, 2004). "Matrix metalloproteinases, in particular the gelatinases MMP-2 and MMP-9, have received great attention in recent years as putative tumour markers for clinical applications." (PMID 15054465, 2004). "In contrast to MMP-2, the proform of MMP-9 increases much more than active MMP-9 during normal to tumour conversion." (PMID 12085179, 2002). "Real-time quantitative RT–PCR analysis was performed on mRNA transcripts of nine genes (VEGF121, VEGF165, VEGF189, VEGF-C, eIF-4E, b-FGF, TSP-2, MMP-2 and MMP-9) involved in angiogenesis and/or lymphangiogenesis as well as tumour cell invasion." (PMID 12189553, 2002). "Significant correlations were found between detection of MT1-MMP and MMP-2 in tumour cell cytoplasm (P< 0.05), of MT1-MMP and TIMP-2 in tumour cell cytoplasm (P< 0.01), and of MMP-2 and TIMP-2 in tumour cell cytoplasm (P< 0.01)." (PMID 10901373, 2000). "Elevated expression of type IV collagenases (MMP-2 and MMP-9) has been strongly correlated with tumour progression and metastasis in various tumours." (PMID 11044366, 2000). "Expression of active MMP-2 and MMP-9 and the total MMP activity were greater in tumour compared to normal samples in both tissues (P< 0.05)." (PMID 10496354, 1999).
tumor (continued). "In addition, some genes including ABCG1, KRAS, MMP2, MMP9 were inhibited by cyAV3.3 in homospheroids, which indicates the direct effect of ITGA5 inhibition on resistance in tumor cells." (PMID 41584360, 2026). "Conversely, exosomes derived from tumor-associated macrophages led to increased expression of TGF-β signaling pathway activators in meningioma cells, specifically TGFBI, SNAI1, MMP2, TGF-β1, TGF-β2, IGFBP7, and LTBP2, leading to tumor cells obtaining a more aggressive phenotype." (PMID 40486962, 2025). "Western blot analyses were subsequently performed to assess the effects of PTEs on the expression levels of matrix metalloproteinases 2 and 9 (MMP2 and MMP9), which are key mediators of cancer progression through their roles in promoting tumor invasion, metastasis, and angiogenesis." (PMID 40723276, 2025). "In addition, GBM-secreted sEVs contain the matrix metalloproteinases (MMPs) MMP-2 and MMP-9 in their crown, which promote extensive hydrolysis of the extracellular matrix and increase tumor aggressiveness." (PMID 39996852, 2025). "Additionally, considering the critical role of matrix metalloproteinases (MMPs) in tumor metastasis, we further examined the effect of SAMD4B on the expression of MMP-2 and MMP-9." (PMID 41154652, 2025). "Specifically, MMP-2 and MMP-9 facilitate tumor metastasis by degrading components of the extracellular matrix, enabling the dissociation of cancer cells from the primary tumor and promoting invasive behavior." (PMID 41153831, 2025). "In some reports, the chlorotoxin (Ctx) polypeptide produced by the scorpion Leiurus quinquestriatus, interacts with human MMP-2 to inhibit tumor invasion without affecting surrounding tissue." (PMID 40791509, 2025). "The results demonstrated that knockdown of ESRRG downregulated PCNA, MMP-2, VIMENTIN, and N-cadherin, while upregulating E-cadherin expression, suggesting that ESRRG may promote tumor migration and invasion by modulating EMT." (PMID 40356747, 2025). "MMP2, known to be regulated by the PI3K-AKT signaling pathway, is a key factor in tumor metastasis." (PMID 40593489, 2025). "Among them, MMP2 and MMP9 play important roles in promoting tumor cell metastasis." (PMID 40520902, 2025). "The current study is a continuation of our previous research, which focused on the role of other proteases such as metalloproteinases (MMP-9 and MMP-2) and their tissue inhibitors (TIMP-1 and TIMP-2) as candidates for tumor markers in gastro-intestinal malignancies, including CRC." (PMID 40725774, 2025). "Moreover, matrix metalloproteinases (MMP2, MMP9)—key mediators of ECM remodeling and metastasis—were significantly elevated, reinforcing the model’s relevance for studying EMT-driven tumor progression." (PMID 41149589, 2025). "Moreover, expression levels of MMP2 and MMP9, known to play key roles in tumor metastasis, decreased following O+C treatment." (PMID 39859407, 2025). "This analysis includes the tumor microenvironment, encompassing the infiltration of immune cells such as CD4+ and CD8+ lymphocytes, macrophage polarization, and increases in certain metalloproteinases (MMP-2 and MMP-9)." (PMID 41516122, 2025). "A dendrimer-based nanoplatform utilizing chlorotoxin (CTX) for MMP2 targeting, conjugated with polyethylene glycol (PEG) and radiolabeled with iodine-131 (131I), has demonstrated high in vivo stability, selective tumor uptake, and dual-functionality for SPECT imaging and β-radiation therapy." (PMID 40806525, 2025). "Principally, TAMs promote tumor cell invasion and dissemination, and through their ability to release cytokines and factors that support growth and ECM-shaping (MMP-2, MMP-9), milk fat globule-EGF factor 8 (MFGE8), IL-6 are correlated with tumor progression and metastasis." (PMID 39981232, 2025). "These MMPs synergistically activate pro-MMP-2, promoting ECM degradation and tumor invasion." (PMID 40265458, 2025).